EIF3M (eukaryotic translation initiation factor 3 subunit M)
Description:
Component of the eukaryotic translation initiation factor 3 (eIF-3) complex, which is required for several steps in the initiation of protein synthesis. The eIF-3 complex associates with the 40S ribosome and facilitates the recruitment of eIF-1, eIF-1A, eIF-2:GTP:methionyl-tRNAi and eIF-5 to form the 43S pre-initiation complex (43S PIC). The eIF-3 complex stimulates mRNA recruitment to the 43S PIC and scanning of the mRNA for AUG recognition. The eIF-3 complex is also required for disassembly and recycling of post-termination ribosomal complexes and subsequently prevents premature joining of the 40S and 60S ribosomal subunits prior to initiation. The eIF-3 complex specifically targets and initiates translation of a subset of mRNAs involved in cell proliferation, including cell cycling, differentiation and apoptosis, and uses different modes of RNA stem-loop binding to exert either translational activation or repression. (Microbial infection) May favor virus entry in case of infection with herpes simplex virus 1 (HSV1) or herpes simplex virus 2 (HSV2).
Synonyms: hFL-B5; PCID1; GA17; FLJ29030; TANGO7; B5
Tractability: Small molecule: a structure with a bound ligand is known. PROTAC: ubiquitination databases record sites on it; its protein half-life has been measured.
Gene: Protein-coding gene on chromosome 11 (32,583,785 to 32,606,264, forward strand). Ensembl gene ENSG00000149100.
Subcellular location: Cytoplasm
Subcellular location (Human Protein Atlas): Cytosol
Pathways (Reactome):
Metabolism of proteins: Formation of a pool of free 40S subunits; Formation of the ternary complex, and subsequently, the 43S complex; GTP hydrolysis and joining of the 60S ribosomal subunit; L13a-mediated translational silencing of Ceruloplasmin expression; Ribosomal scanning and start codon recognition; Translation initiation complex formation
Gene Ontology:
Molecular function: protein binding; translation initiation factor activity; translation initiation factor binding
Biological process: cytoplasmic translational initiation; formation of cytoplasmic translation initiation complex; translational initiation
Cellular component: eukaryotic translation initiation factor 3 complex; cytosol; cytoplasm; eukaryotic 43S preinitiation complex; eukaryotic 48S preinitiation complex; eukaryotic translation initiation factor 3 complex, eIF3m; protein-containing complex
Genetic constraint (gnomAD): Loss-of-function variants: 19 observed, 44.2 expected, observed/expected ratio (o/e) 0.43, 90% interval 0.3 to 0.63. The upper end of that interval is the gene's LOEUF score, 0.63, which puts it in group 2 of 6, group 1 being the genes least tolerant of losing a copy. Missense variants: 343 observed, 436.85 expected, observed/expected ratio (o/e) 0.79, 90% interval 0.72 to 0.86. Synonymous variants: 153 observed, 149.75 expected, observed/expected ratio (o/e) 1.02, 90% interval 0.89 to 1.17.
Homologues: Orthologues: chimpanzee EIF3M (100% identical), dog EIF3M (100% identical), macaque EIF3M (100% identical), pig EIF3M (99% identical), mouse Eif3m (99% identical), guinea pig EIF3M (99% identical), rat Eif3m (94% identical), tropical clawed frog eif3m (89% identical), zebrafish eif3m (88% identical), Drosophila melanogaster eIF3m (47% identical), Caenorhabditis elegans cif-1 (31% identical). Paralogues in human: COPS7B (13% identical), COPS7A (13% identical).